IL6 (interleukin 6)
Diseases named in the same sentence as IL6 in open-access papers (continued):
Sharing a sentence is not in itself a finding about the gene and the disease.
lymphoma (continued). "Although the IL6-/-;Eμ-myc lymphomas were comprised of more mature B cells, pre-tumor bone marrows showed an increase in pre-B immature cells compared with IL6+/+;Eμ-myc mice." (PMID 33651821, 2021). "Gelatin has also been shown to regulate the production and secretion of IL-6 and TNFα in differentiated U937 lymphoma cells." (PMID 34821368, 2021). "Using the Eμ-myc lymphoma mouse model, we demonstrate that IL-6 is a critical tumor promoter during early stages of B cell lymphomagenesis." (PMID 33651821, 2021). "To further characterize protein expression dependent on IL-6 and MYC, we evaluated global protein expression profiles in bone marrow of IL6+/+ and IL6-/- mice as well as in lymphomas from IL6+/+;Eμ-myc and IL6-/-;Eμ-myc mice." (PMID 33651821, 2021). "As first implemented, the test involved an ELISA of the vitreous fluid: the levels of IL-10 and IL-6 were compared directly, and if greater than one, the result was taken to indicate lymphoma." (PMID 34439078, 2021). "Histopathological analysis revealed that control IL6+/+;Eμ-myc mice developed advanced lymphomas with massive enlargement of lymph nodes [94% of the cases], spleen [50%] and thymus [50%], in agreement with previous reports." (PMID 33651821, 2021). "We found that the Kyn/Trp ratio in all lymphoma survivors analyzed was significantly correlated with other markers of immune activation and inflammation, such as measurable levels of IL-6, neopterin and CRP." (PMID 31923274, 2020). "The cytokines IL-4, IL-6, IL-10 and TNFα are produced by T cells, but often also by activated lymphoma cells or macrophages." (PMID 32899476, 2020). "Increased secretion of interleukine 6 (IL6) was responsible for acquired resistance of lymphoma cells to PI3K inhibitors." (PMID 32197371, 2020). "Although TNF-α has anti-apoptotic signals via the nuclear transcription factor (NF)-κB pathway, it influences lymphoma development through pro-inflammatory cytokines such as IL-1β, IL-6, and IL-8." (PMID 30814315, 2019). "Primary DLBCL cells and DLBCL cell lines expressing IL‐6R engraft and form orthotopic lymphomas in humanized mice that ectopically produce human IL‐6, and in mice reconstituted with a human immune system." (PMID 31515941, 2019). "This is consistent with our previous reports on the effect of IL-6 on malignant cell growth in WM, where IL-6 induced a modest increase in WM cell proliferation in this indolent lymphoma." (PMID 31164961, 2019). "Numerous researchers have demonstrated that MSCs facilitate lymphoma growth by secreting pro-tumor cytokines (such as IL-6 and IL-10), inducing angiogenesis, promoting epithelial and mesenchymal transition, and inhibiting apoptosis of tumor cells." (PMID 30755239, 2019). "One mechanism by which KSHV is known to induce cancer involves interleukin-6 (IL-6), a cytokine that promotes cell growth, angiogenesis and lymphoma formation." (PMID 30126238, 2018). "Gilbert and Hemann’s study in lymphoma model described an interleukin 6 (IL-6)-triggered cytokine-chain response that can promote therapeutic resistance to genotoxic chemotherapy of lymphoma cells." (PMID 30052635, 2018). "For Δ122/+ IL-6+/+ mice there was extensive lymphoma spread evident in 56% (5/9) of cases involving the lungs, liver, pancreas, gut, lymph nodes and other organs." (PMID 29343721, 2018). "KSHV infection induces tumorigenesis through upregulation of host interleukin-6 (IL-6), a cytokine that promotes cell growth, angiogenesis, and lymphoma formation." (PMID 30126238, 2018). "Coculture of M(IFN-γ/LPS) macrophages with apoptotic lymphoma cells significantly increased the expression of Mrc1, Timp2, Cd36, Pparg and Gas6, whereas the expression of Tnf and Il6 were significantly decreased." (PMID 28157210, 2017). "STAT3 activation depends on the production of cytokines such as IL-6 produced by the tumor itself or encoded by KSHV, whose infection plays a pivotal role in the pathogenesis of this lymphoma." (PMID 26338963, 2015).
lymphoma (continued). "For instance, drug treated endothelial cells release IL-6 and Timp-1, which promote the induction of Bcl-xl in adjacent lymphoma cells." (PMID 25185441, 2014). "The use of a combination of the cytokine profiles IL-10/IL-6 and IL-10/IFN-gamma was recently shown to be quite effective as a diagnostic adjunct for discriminating lymphoma from uveitis." (PMID 23750271, 2013). "Prior studies, have demonstrated elevated IL-10 levels in patients with lymphoma as well as elevated IL-10/IL-6 levels in lymphoma compared to uveitis." (PMID 23750271, 2013). "Compared to lymphoma or solid tumors (n = 20), acute leukemia subjects (n = 15) displayed significantly higher concentrations (P<0.05) of IL-6, IL-8, IL-10, and TNF-α and lower levels of pro-LL-37 (P<0.001)." (PMID 23741421, 2013). "In one study, doxorubicin treatment of an in vivo lymphoma model led to the release of Il-6 in the tumor microenvironment, creating a chemoprotective niche for maintenance of residual cells." (PMID 23520493, 2013). "Our findings demonstrate that aqueous levels of IL-10 and IL-10/IL-6 are elevated in lymphoma compared to uveitis." (PMID 23750271, 2013). "Elevated serum levels of IL-6 have also been observed 1–3 years prior to the onset of AIDS-NHL, thus supporting the role of IL-6-driven B cell stimulation in the development of these lymphomas." (PMID 24151490, 2013). "In our analysis, we selected the highest IL-10 and lowest IL-6 values in each patient with lymphoma and the lowest IL-10 and highest IL-6 values in each patient with uveitis." (PMID 23750271, 2013). "These KSHV-infected B-cell lymphomas critically depend on constitutive NF-κB activity that mediates enhanced production of lymphoma cell survival factors such as IL-6." (PMID 23300567, 2012). "A strong positive correlation exists between development of post-transplant EBV-lymphomas in humans and elevated levels of serum IL6." (PMID 21352549, 2011). "This primarily occurs because cytokines (such as interleukin-6, interferon-gamma, etc) secreted by lymphoma lead to a hyperinflammatory state, which may contribute to the development of HLH." (PMID 41559979, 2026). "Interleukin 6 (IL6) has been reported to be involved in the transformation of MC to lymphoma." (PMID 37345190, 2023). "Interestingly, the knockdown of STAT3 in A20 lymphoma also leads to a reduced IL-6 production in tumor-bearing mice." (PMID 37686472, 2023). "On the basis of MSCs homing toward tumor region and the combination of CD20 antibody to CD20-positive B cell lymphocytes, UCMSCs-Tandab(IL-6/CD20) could effectively inhibit the viability of lymphoma cells in the ex vivo experiment." (PMID 36104733, 2022). "A novel UCMSCs-Tandab(IL-6/CD20) could be used to bind with the CD20-positive lymphoma cells and pro-tumor cytokines IL-6, target and kill tumor cells." (PMID 36104733, 2022). "In addition, 15 patients were tested for IL-6 and IL-10 levels to assess inflammatory status and diagnose lymphoma." (PMID 35439966, 2022). "Therefore, after co-cultured with lymphoma cells, Tandab (IL-6/CD20) protein competitively inhibited the binding of human CD20 monoclonal antibody to the CD20 antigen." (PMID 36104733, 2022). "Interestingly, past research has shown that estrogen can inhibit lymphoma in female patients by reducing serum IL-6, so the incidence of lymphoma in women is generally lower in women than in men." (PMID 35683570, 2022). "ATA B CLL/lymphoma cells were IL-6+, and IL-6-binding Arid5a75 was also increased." (PMID 36050343, 2022). "Therefore, we focused on STAT3 as a potential downstream mediator of IL-6 action in Eμ-myc lymphomas." (PMID 33651821, 2021). "Furthermore, IL6-/-;Eμ-myc lymphomas transplanted into syngeneic IL-6+/+ or IL6-/- mice retained PTEN and BIM expression." (PMID 33651821, 2021). "To determine whether the increase in BIM and PTEN protein expression in IL-6-/-;Eμ-myc lymphoma cells reflected an increase in their mRNA expression, we compared mRNA levels." (PMID 33651821, 2021).
lymphoma (continued). "We analyzed a variety of clinical factors (gender, age, risk stratification, clinical stage, CAR-T cell dose, serum peak concentration of IL-6 and CRP, CD4/CD8, etc.)that may be associated with CRS in patients with lymphoma, separately." (PMID 33708205, 2021). "Later studies showed that a similar IL-10/IL-6 ratio could be measured in the aqueous, which can be readily collected for serial measurements to follow lymphoma over time." (PMID 34439078, 2021). "Indeed, the IL-6 levels do not decline even after years of successful ART, and the enhanced levels of IL-6 and other B cell stimulatory molecules precede lymphoma development." (PMID 34372605, 2021). "Although the bone marrow of young pre-malignant IL6-/-:Eμ-myc mice have an increase in immature pre-B cells, the B lymphomas that develop in adult IL6-/-:Eμ-myc mice have a mature phenotype in comparison with IL6+/+:Eμ-myc lymphomas." (PMID 33651821, 2021). "PAL is an aggressive lymphoma with strong Ki-67 expression in almost all patients, different from Castleman's disease with high interleukin-6 (IL-6) expression, heterotopic ossification, and benign micro-nodular hyperplasia appeared in proximity to the lymphatic tissue invading the adrenal." (PMID 33071959, 2020). "In this study, CD37 has been discovered to interact with suppressor of cytokine signaling 3 (SOCS3), and its absence was hypothesized to drive lymphoma development through constitutive activation of the IL-6 signaling pathway." (PMID 33333768, 2020). "It indicates a potential role for sex hormones working in the pathogenesis of PHL and Recently, multiple studies have demonstrated that estrogen served a protective role through decreasing the level of serum IL-6 interleukin-6 and thereby inhibited lymphoma in female patients." (PMID 32477954, 2020). "IL6-triggered Janus kinase(JAK)- signal transducer and activator of transcription (STAT) cascade was reported as a critical molecular mechanism underlying resistance of lymphoma cells to copanlisib and duvelisib." (PMID 32197371, 2020). "Interestingly, MISTRG recipients that had been reconstituted at birth with a normal human immune system promoted lymphoma engraftment in the bone marrow as efficiently as mice expressing IL‐6." (PMID 31515941, 2019). "Interleukin-6 (IL-6) is produced at high levels by inflammatory cells in uveitis, whereas IL-10 is produced by malignant B lymphocytes in intraocular and central nervous system (CNS) lymphoma." (PMID 31635036, 2019). "Indeed, lymphoma-derived small EVs efficiently interact with monocytes by membrane fusion, inducing secretion of the pro-inflammatory cytokines IL-6, TNF-α, IL-1β, and profoundly altering the process of their differentiation into dendritic cells." (PMID 31137912, 2019). "MAPK and NF-κB, which remain active in IL-6–high lymphoma cells, may promote continued survival and growth, even upon PI3K inhibition." (PMID 31601188, 2019). "Whether the inhibition of IL-6 is a key factor in inhibition of RLS-40 lymphosarcoma growth remains to be seen in future experiments." (PMID 27538520, 2016). "Comparing PCT and IL-6 among solid tumor and lymphoma patients with different cancer stages." (PMID 26148092, 2015). "We also investigated the suppressive effect of IL-6 on more physiological immune responses of endogenous CD4+ T cells in protecting aged mice against the outgrowth of murine leukaemia virus (MuLV)-induced lymphoma, RMA21." (PMID 25850032, 2015). "Here, we evaluate the utility of IL-10, IL-6 and IL-10/IL-6 for discriminating lymphoma from uveitis and report the effects of intraocular methotrexate and rituximab on aqueous cytokine levels in eyes with lymphoma." (PMID 23750271, 2013). "Selecting the highest IL-10 and lowest IL-6 level for each patient with lymphoma and the lowest IL-10 and highest IL-6 level for each patient with uveitis yielded a total of 10 data points from 10 patients with lymphoma and 7 data points from 7 patients with uveitis." (PMID 23750271, 2013).
lymphoma (continued). "Statistical indices for threshold values of IL-6 for discriminating lymphoma from uveitis." (PMID 23750271, 2013). "Compared to eyes with uveitis, eyes with lymphoma had higher levels of IL-10 (U = 7.0; two-tailed p = 0.004) and IL-10/IL-6 (U = 6.0; two-tailed p = 0.003), whereas IL-6 levels were more elevated, although insignificant, in those patients with uveitis than in lymphoma (U = 15.0; two-tailed p = ns)." (PMID 23750271, 2013). "Osm (oncostatin M), a cytokine in the interleukin 6 group originally identified to inhibit cell growth in lymphoma cells, was significantly decreased in both DA-1 and NFS-60 leukemic cells (13-fold decrease, p<0.0004 and 1.8-fold decrease, p<0.04, respectively)." (PMID 23826213, 2013). "Statistical indices for threshold values of IL-10/IL-6 for discriminating lymphoma from uveitis." (PMID 23750271, 2013). "Additionally, in our study, both IL-10 and IL-10/IL-6 cytokine markers were moderately accurate tools for discriminating lymphoma from uveitis." (PMID 23750271, 2013). "Similarly, IL-10/IL-6 levels were significantly elevated in eyes with lymphoma (U = 6.0; two-tailed p = 0.003)." (PMID 23750271, 2013). "In pyothorax-associated lymphoma, transformation of lymphocytes caused by EBV infection and proliferative stimulation via inflammatory cytokines including interleukin-6 in the microenvironment of chronic pyothorax might be the major cause of tumorigenesis." (PMID 22931631, 2012). "Because they can stimulate the production of interleukin (IL)-6 in periphereal mononuclear cells and lymphoma cells in vitro it has been hypothesized, that they promote tumor enhancement of related malignancies." (PMID 22114899, 2011). "Also, since stromal elements were supporting DS-1 cell proliferation, these could also have been targeted by IL-6 trans-signaling inhibitor, leading to diminished local IL-6 secretion and overall impairment of stromal and lymphoma cell proliferation." (PMID 38980514, 2025). "In our lymphoma-on-chip model, we detected IL-6 in the luminal supernatant when FRCs were present in the hydrogel, and IL-6 levels increased when both FRCs and DLBCL cells were present, supporting the hypothesis that FRCs are the source of high IL-6 levels in DLBCL." (PMID 40061210, 2025). "Some more obvious cytokines such as IL-2, IL-6, IL-7, and IL-15 have a direct link with T-cell lymphoma progression, and these cytokines’ expression levels have the potential to be used as biomarkers especially to predict the developmental stage of T-lymphoma tumor cells." (PMID 37746258, 2023). "Indeed, STAT3 was further activated by IL-6 after being treated with 15 min in A20 lymphoma." (PMID 37686472, 2023). "Anti-IL-6 antibody could abrogate the IL-6/IL-6R axis and promote the apoptosis of lymphoma cells." (PMID 36104733, 2022). "Thus, we propose that Arid5a-IL-6 interactions in CD1d– (IL-5R–) B1 B cells may have promoted the development of lymphoma, different from NKT2 connecting CD1d+B1 B cells." (PMID 36050343, 2022). "Moreover, an immunosuppressive tumor microenvironment, with tons of interleukin 6 (IL-6), IL-10, EBV-encoded microRNAs, and C-C motif chemokine receptor 4 (CCR-4)+ regulatory T-cells (Treg), may aid lymphoma cell survival in immunocompetent individuals." (PMID 33564306, 2021). "The slower development of Eμ-myc lymphomas deficient in IL-6 may rely on activation of non-STAT pathways such as MAPK/ERK and PI3K/AKT, or STAT pathways activated by other cytokines." (PMID 33651821, 2021).
lymphoma (continued). "Thus, combined with previously discussed effects of viral ORF57 competition for cellular miRNA target sites on expression of vIL-6 and IL-6 mRNAs, this leads to a further upregulation of IL-6 expression, further promoting cell growth, angiogenesis and lymphoma formation." (PMID 30126238, 2018). "In this study a comprehensive analysis of the systemic levels of interleukins (IL-1,IL-6, IL-8,IL-10 and IL-12) was performed in 75 patients with different gastric neoplasms (cancer, gastrointestinal stromal tumors, neuroendocrine neoplasms, lymphomas) and 40 healthy volunteers." (PMID 26486258, 2015). "However, elevated IL-10 and IL-10/IL-6 values are indicative of lymphoma." (PMID 23750271, 2013). "IFN-γ KO/KD also did not decrease the efficacy of anti-CD19 CAR Ts against leukemia/lymphoma models, while decreased the levels of some inflammatory cytokines (MCP-1, MIP-1β, IL-6, TNF-α, and IP-10) and macrophage activity markers (CD80 and CD86)." (PMID 41354926, 2025). "Consistent with the results of preclinical study, the contents of IL-1ra, IL-6, IL-8, CXCL10, MCP-1, and IFN-γ in serum of the response MM and lymphoma patients were increased after one week of PM treatment." (PMID 40562746, 2025). "Previous study showed high levels of IL-10, IL-6, IL-1β, and TNF-α in lymphoma patients except TNF-α in NHL patients." (PMID 40076681, 2025). "The utilization of IL-6 inhibitors and JAK inhibitors in severe COVID-19 cases required careful consideration, especially for lymphoma patients with B-cell aplasia." (PMID 40978033, 2025). "Lymphoma cells enhanced the expression of p-PERK, p-IRE1α, ATF6, IL-6, IL-4, p-AKT, CD9, CD63 and PD-L1 in bone marrow-derived macrophages by mediating the Notch-1 signaling pathway." (PMID 38261741, 2024). "Another scoring system termed – the Interleukin Score for intraOcular Lymphoma Diagnosis (ISOLD) – was also proven to be promising in predicting the likelihood of intraocular lymphoma based on IL-10 and IL-6 value." (PMID 38324143, 2024). "In the CSF + LM (lymphoma) vs. CSF − LM comparison, ITGB1, IL6, ABL1, CYCS, among others, were differentially observed and expressed in cancer cells." (PMID 35053611, 2022). "We have found that IL-6 induces chemotherapy resistance for rituximab (anti-CD20 monoclonal antibody), protects lymphoma cells from spontaneous and drug-induced apoptosis, and eventually promotes the growth of DLBCL through JAK/STAT3 and PI3K/Akt pathway." (PMID 36104733, 2022). "A recent study found that IL6, IL8, TNF, and other cytokines expression varies in lymphoma patients (both HL and NHL) and health populations." (PMID 35452413, 2022). "As lymphomas arose, enhanced expression of both BIM and PTEN accompanied ~90% of tumors arising in IL6-/-;Eμ-myc mice." (PMID 33651821, 2021). "Prior to the onset of frank lymphoma, low variable levels of BIM and PTEN were expressed in Eμ-myc cells of both IL-6 genotypes." (PMID 33651821, 2021). "At diagnosis, IL10, IL6 and BAFF cytokine serum levels were higher in cHL patients with advanced-stage (Ann Arbor III-IV) lymphoma compared to patients with localized disease (p = 0.002, p = 0.03 and p = 0.01, respectively)." (PMID 35008292, 2021). "Overall, lymphoma patients had rising inflammatory markers in routine laboratory testing at the time of clinical deterioration, including C-reactive protein (CRP) and IL-6 serum levels." (PMID 34235400, 2021). "Dogs with lymphoma have higher circulating macrophage chemoattractant protein-1 (MCP-1), VEGF, IL-6, IL-10 and lower transforming growth factor-β (TGF- β) than healthy dogs." (PMID 30987001, 2019).